CSNK2A1 (casein kinase 2 alpha 1)
Diseases named in the same sentence as CSNK2A1 in open-access papers (continued):
Sharing a sentence is not in itself a finding about the gene and the disease.
tumor-predisposition syndromes (1 paper, 2025).
cancer (69 papers, 2008 to 2025). A tumor composed of atypical neoplastic, often pleomorphic cells that invade other tissues. "Our data analysis revealed proteins associated with elevated CSNK2A1 levels in ESCC that were also correlated with tumor maintenance in other cancer types." (PMID 38652547, 2024). "The core-clock genes NR1D1, PER3, CSNK2A1, and the cancer associated gene VEGFA showed statistically significant results in our Cox-regression based survival plots (log rank test p ≤ 0.05)." (PMID 32295075, 2020). "Casein kinase 2α1 (CSNK2A1) encodes the protein kinase CK2α, which phosphorylates various proteins and regulates biological processes such as the cell cycle and apoptosis, also affecting the Wnt/β-catenin signalling pathway, which plays an important role in cancer." (PMID 40028162, 2025). "CSNK2A1, a serine/threonine kinase, is involved in cancer‐related processes such as cell cycle regulation, apoptosis inhibition, and DNA damage repair." (PMID 41377767, 2025). "These conclusions strongly reveal that CSNK2A1 has a substantial role in advancing human cancers and holds the potential as a prognostic marker for various types of malignancies." (PMID 37348024, 2023). "CSNK2A1 has been previoulsy reported to be a predictive biomarker and a therapeutic target in different types of cancer." (PMID 37047552, 2023). "Functionally crucial for cell development and commonly dysregulated in cancer, CSNK2 is a pleiotropic serine/threonine kinase encoded by two distinct catalytic isoforms (CSNK2A1 and CSNK2A2) that can form complexes with a regulatory subunit (CSNK2B)." (PMID 34773100, 2022). "The overexpression of the CSNK2A1 subunit in different types of cancer makes this enzyme a strong target candidate for cancer treatment." (PMID 35565454, 2022). "These biological roles of CSNK2A1 in cancer are closely related to its kinase activity on the targets involved in tumorigenesis." (PMID 34359939, 2021). "The mechanism by which CSNK2A1 renders a resistance phenotype to cancer cells has been suggested to be by suppressing the apoptotic signaling of cancer cells." (PMID 34359939, 2021). "CSNK2A1 serves cancer progression by inducing the phosphorylation of various molecules, including SIRT1, SIRT6, and CCAR2." (PMID 34359939, 2021). "CSNK2 α1 (CSNK2A1, CK2α) expression is also elevated in cancer tissue of the gastrointestinal tract, head and neck, kidney, and prostate." (PMID 34359939, 2021). "CSNK2A1 is involved in cancer progression by regulating various cancer-promoting signaling pathways, such as the MYC, PI3K-Akt, NFκB, and Wnt/β-catenin pathways." (PMID 34359939, 2021). "At the transcriptional and/or protein level, CK2 overexpression, particularly in the α catalytic subunit (CK2α or CSNK2A1), has been observed in many cancers." (PMID 31929734, 2020). "Some of the identified factors (such as TSPAN8, CXCL17, CRIP2, STARD10, CSNK2A1) and pathways (i.e. apoptosis, TGFβ, VEGF and ERK signaling) are known to participate in cancer as well as their identification here linked with airway remodeling in mustard lung." (PMID 24978043, 2014). "Consequently, investigating the function and regulatory mechanisms of CSNK2A1 holds immense significance in clinical cancer treatment." (PMID 37348024, 2023). "Thus, widespread CSNK2 dysregulation, combined with data from prior studies that overexpression of CSNK2A1 can lead to in vivo oncogenic transformation, strongly suggests an important role in cancer." (PMID 34773100, 2022). "Previous studies have revealed that CSNK2A1 is biologically important in multiple malignant tumors." (PMID 35266446, 2022). "CSNK2A3 might have an advantage over the CSNK2A1 in cancer cells in which sophisticated lineage-specific gene (s) expression is necessary." (PMID 35123428, 2022). "The CSNK2A3 might have an advantage over the CSNK2A1 in cancer cells in which sophisticated lineage-specific gene expression is necessary." (PMID 35123428, 2022).
cancer (continued). "Several additional chemicals inhibiting CSNK2A1 are under evaluation in human cancers." (PMID 34359939, 2021). "Therefore, in conjunction with previous reports and this study, it is suggested that the CSNK2A1-mediated phosphorylation of SIRT6 on Ser338 is important in rescuing injured cancer cells by repairing DNA damage induced by anti-cancer therapeutics." (PMID 34359939, 2021). "Consequently, CSNK2A1 promotes the proliferation and invasiveness of cancer cells by activating cell-cycle progression and the epithelial-to-mesenchymal transition (EMT)." (PMID 34359939, 2021). "CSNK2A1 is amplified in some cancers albeit at a relatively low frequency." (PMID 36045705, 2021). "Moreover, CSNK2A1 renders cancer cells resistant to apoptotic stresses by activating BCL2 and suppressing PML, FOXO3, and PARP1." (PMID 34359939, 2021). "CK2α/CSNK2A1 is involved in cancer progression by phosphorylating various signaling molecules." (PMID 34359939, 2021). "The intersection of differentially expressed genes (DEG) and our list of candidate genes, resulted in 12 elements including cancer associated genes (NRAS, MYC, and VEGFA), circadian drug targets (SOD2 and CES2) and core-clock and ECCN genes (AHR, CREB1, CSNK2A1, NFIL, NPAS2, NR1D1, and PER3)." (PMID 32295075, 2020). "NF-κB-based GRNs clearly illustrated group-specific disturbances, with the cancer-related casein kinase CSNK2A1 being a target gene only in the carcinogenic group, and opposite regulation of NF-κB subunits being observed in DILI and non-DILI/non-carcinogenic groups." (PMID 29085386, 2017). "Instead, the Pathways in cancer genes Kras, Met, Figf, Hgf, Fgf7, Ctnnb1 and Tcf7l1, and directly interacting genes Nr3c2 and Csnk2a1 may lead to new insights in US28-mediated signaling and ultimately the oncomodulatory role of HCMV." (PMID 25002203, 2014). "Concerning these results, when considering the molecular mechanism of CSNK2A1 in cancer to be used as a therapeutic target, the molecular network related to CSNK2A1 is complex, because CSNK2A1 might also be protective for molecules that might have tumor-suppressive roles." (PMID 34359939, 2021). "Notably, CSNK2A1 has been found to be highly expressed in a wide variety of cancers." (PMID 31929734, 2020). "Although the activity of the CSNK2A1 gene has been shown to be elevated in human cancers, no solid genetic or epigenetic evidence is available regarding the cause of the high-activity of CK2α in cancer cells." (PMID 20625391, 2010). "We also observed that HDAC8 expression was positively correlated with CSNK2A1, CSNK2A2, and CSNK2B in multiple cancer types in public databases." (PMID 40013761, 2025). "We observed an upregulation of CTNNB1 and other genes involved in CTNNB1 stabilization (CSNK2A1, CSNK2B, DVL2, DVL3,) in rHGP cancer areas." (PMID 36691028, 2023). "CSNK2A1, a catalytic subunit of Casein kinase II (CSNK2), has been recognized as participating in different cancer cells’ invasive and migratory processes by triggering epithelial-mesenchymal transformation (EMT)." (PMID 37348024, 2023). "Among them, genes such as BCL2, CSNK2A1, EGFR, PDGFRA, VEGFA, etc., which have been proved to be targets of anti-cancer drugs, were proposed to provide general administrations for pan-cancers." (PMID 32523951, 2020). "In the GBM dataset, CSNK2A1 and TTN are similarly identified as potential cancer genes as in NCG." (PMID 38510118, 2024). "However, further investigation is required to find out the expression of CSNK2A1 and CSNK2A3 in various cancer cells employing strategies that can distinguish expression from one another." (PMID 35123428, 2022).
cancer (continued). "Consistently, the expression of CSNK2A1 was elevated in cancers compared with non-cancerous tissues in the colorectum, head and neck, kidney, prostate, and stomach." (PMID 34359939, 2021). "CSNK2A1 engages the MYC, Akt, and NFκB pathways to stimulate the proliferation of cancer cells." (PMID 34359939, 2021). "Considering the role of CSNK2A1 in cancer progression and the phosphorylation of SIRT6 and the role of SIRT6 in chemoresistance through the DNA damage repair pathway, CSNK2A1 and SIRT6 might be involved in resistance to conventional anti-cancer therapies." (PMID 34359939, 2021). "To date, there is no genetic or epigenetic evidence on the activation of the CSNK2A1 gene in human cancer." (PMID 20625391, 2010). "Therefore, the relationship between CSNK2A1 and SIRT6 phosphorylation on Ser338 might be important in cancer therapy with regards to overcoming resistance to anti-cancer therapeutics." (PMID 34359939, 2021). "Therefore, both blocking CSNK2A1 and SIRT6 or the direct suppression of the DNA damage repair pathway might be promising therapeutic strategies to overcome cancer resistance to conventional genotoxic anti-cancer therapeutics." (PMID 34359939, 2021). "There were a larger number of kinases specifically dysregulated in cancer (e.g. PRKACA, CSNK2A1 and MAPK1) compared with other noncancer conditions." (PMID 36688815, 2023).
tumor (45 papers, 2007 to 2025). "Given the crucial role of M0 macrophages and mast cells in the tumour microenvironment, the associations between CSNK2A1,SNAI1,and these immune cells deserve further investigation." (PMID 40028162, 2025). "As a known target for tumor, casin kinase 2α1 (encoded by CSNK2A1) play key roles in cell cycle regulation, cellular differentiation, proliferation and apoptosis regulation." (PMID 34211501, 2021). "With these cut-off points, CSNK2A1-positivity was significantly associated with sex (p = 0.046), higher tumor stage (p = 0.006), higher T category (p = 0.028), higher M category (p = 0.047), latent distant metastasis (p = 0.025), and pSIRT6-positivity (p < 0.001)." (PMID 34359939, 2021). "Specifically, CSNK2A1/3 was identified as highly ranking in the P0422-T1 tumor line and the kinases CAMKK2 and PIP4K2C were identified in the P0119-T1 CAF line." (PMID 39221276, 2024). "This growth inhibitory phenotype translated to the in vivo setting where PDAC xenograft models with CSNK2A1 silenced by siRNA had decreased tumor volume compared to siRN control mice." (PMID 39221276, 2024). "Our results demonstrate a reduction in tumor volumes and weights upon knockdown of CSNK2A1 compared with those in the scramble group, resulting in an approximately 60% suppression rate." (PMID 38652547, 2024). "CSNK2A1 has been shown to affect tumor recurrence, metastasis, and prognosis through the phosphorylation of various substrates, making it a key target for anti-tumor therapy." (PMID 36306106, 2023). "Experiments in vivo exhibited that intratumoral delivery of these complexes to subcutaneous ovarian tumors not only significantly suppressed tumor growth and migration of tumor cells but also led to reducing CSNK2A1 mRNA and CK2α protein expression." (PMID 37109432, 2023). "Multivariate analysis for OS and RFS was performed with the inclusion of age, tumor size, stage, T category, N category, M category, pSIRT6 expression, and CSNK2A1 expression." (PMID 34359939, 2021). "Copy number variation analysis showed that CSNK2A1, HTATSF1, and TOPBP1 gain copy number and their amplification is tightly associated with expression, suggesting a possible genomic cooption for the three genes during tumor evolution." (PMID 38762174, 2024). "Our results demonstrate that depletion of CSNK2A1 profoundly impeded tumor growth in vivo." (PMID 38652547, 2024). "Reportedly, CSNK2A1 is expressed at abnormally high levels and kinase activity in a variety of cancer cells, and it stimulates tumor proliferation, DNA damage repair, EMT, drug resistance, and other biological behaviors by phosphorylating key molecules in various signaling pathways." (PMID 36306106, 2023). "Interestingly, CX-4945 treatment lowered HMGB1, β-catenin, C-MYC, phosphor-MAX, IL-6, and CSNK2A1 protein levels in tumor tissues in CX-4945 treatment as compared with a vehicle." (PMID 37347224, 2023). "The molecular mechanisms and roles of CSNK2A1 in tumorigenesis have been extensively investigated, and it has been shown that CSNK2A1 is involved in tumorigenesis by its roles as a kinase to activate oncogenic molecules and to stimulate degradation of tumor suppressors." (PMID 34359939, 2021). "Notably, CSNK2A1 has been found as an oncogene in multiple tumor types." (PMID 37348024, 2023). "In particular, cell cycle genes such as CSNK2A1, MCM8, CDK19, KIFC1 and MCM7, among which KIFC1 was previously found to be a factor for poor prognostic and a therapeutic target associated with tumour proliferation in HCC34,35, even though its immunodulatory function has never been described before." (PMID 33431814, 2021). "Notably, CSNK2A1 exhibited significant correlations with 27 phosphosubstrates specifically within the S_I subtype, indicating it may be crucial in sustaining the malignant tumor phenotype." (PMID 41377767, 2025).
tumor (continued). "To further validate the effect of p-CSNK2A1 T360/S362 on tumor growth in ESCC, we measured expression and phosphorylation levels of CSNK2A1 and HDAC1 in tumor samples obtained from our PDX models by Western blotting." (PMID 38652547, 2024). "This shows a potential tumor selective vulnerability that can be exploited in PDAC or a subset of PDAC patients since CSNK2A1/3 and CSNK2B were top features in only one of the tumor cell models, P0422-T1." (PMID 39221276, 2024). "To elucidate the specific contribution of CSNK2A1 to tumor growth, we conducted an in vivo knockdown experiment using LEG244 PDX model mice by employing lentivirus-mediated shRNA delivery targeting CSNK2A1." (PMID 38652547, 2024). "Our study reveals that inhibition of CSNK2A1 attenuated cell proliferation and suppressed ESCC tumor growth in vivo." (PMID 38652547, 2024). "These included Casein Kinase 2 Alpha 1 (CSNK2A1), related to invasion, metastasis, tumour proliferation, in HCT116_WT and HCT116KO." (PMID 35552415, 2022). "Additionally, both S609 on FGA and S1943 on MYH9 are phosphorylated by CSNK2A1, a subunit of the protein kinase CK2 which phosphorylates many TFs in tumor cells." (PMID 40453647, 2025). "Among the analyzed genes, only CSNK2A1, which encodes the catalytic subunit of CK2, exhibited significantly higher expression in tumor-derived epithelial cells compared to healthy or adjacent normal epithelial cells." (PMID 41145488, 2025). "Of note, silencing CSNK2A1 significantly increased apoptosis in MiaPaCa2 cells but not in the other 11 non-pancreatic human tumor cell lines." (PMID 39221276, 2024). "In addition, Gliovis’ findings showed that, except for CSNK2A1, the remaining ten genes displayed a significant variation between the GBM and the non-tumor condition." (PMID 37370767, 2023). "Additionally, while we validated the feature genes and confirmed our research findings, only three genes' expressions (CSNK2A1, FUNDC1, and SRC) in tumor cells supported our results." (PMID 38155968, 2023). "CX‐4945, a CSNK2A1 inhibitor, could inhibit the phosphorylation of HMGA2 and sensitize tumor cells to cisplatin." (PMID 34115920, 2021). "Moreover, CSNK2A1 mRNA is highly expressed in several tumor types including CCA, and, across all tumor types, high CSNK2A1 expression correlates with poor overall survival." (PMID 36045705, 2021). "Two additional genes (CD14 and CSNK2A1) were dysregulated in MSS tumours and two genes (CARD11 and VCAM1) were downregulated and six genes were upregulated (LYN, TICAM2, ICAM1, IL1B, CCL4 and PTGS2) in MSI tumours." (PMID 29188362, 2018).
infection (9 papers, 2011 to 2025). The state of being infected such as from the introduction of a foreign agent such as serum, vaccine, antigenic substance or organism. "Host proteins enriched at cellular replication forks during infection included DNA processing factors such as GINS, TOP2A, PRIM1/2, RPA2 and XRCC1; DDR signaling proteins such as CSNK2A1/3; cell cycle regulator proteins such as TFDP2 and SFN1; as expected for cells undergoing replication stress." (PMID 40825038, 2025).
neurodevelopmental disorder (3 papers, 2019 to 2023). A behavioral and cognitive disorder with onset during the developmental period that involves impaired or aberrant development of intellectual, motor, or social functions. "Interestingly, mutations in CSNK2A1 and CSNK2B have been found in patients affected by neurodevelopmental disorders (NDDs), which combine intellectual disability, autism spectrum disorder, and general developmental delay." (PMID 31779225, 2019). "Recently, mutations in CSNK2A1 and CSNK2B genes, encoding for α catalytic subunit and β regulatory subunits, respectively, have been found in patients with neurodevelopmental disorders (NDDs), but the functional role of CK2 has not been elucidated in these works." (PMID 31779225, 2019).
genetic diseases (2 papers, 2025). "Our results expanded the spectrum of pathogenic mutations in the CSNK2A1 gene, and offers theoretical support and research ideas for future studies on related genetic diseases." (PMID 41216289, 2025).
CSNK2A1 also shares sentences with these, for which no sentence is quoted: Intellectual disability (6 papers); colon cancer (5); developmental delay (5); glioblastoma (4); kidney cancer (4); viral infection (4); hepatocellular carcinoma (3); leukemia (3); multiple myeloma (3); Alzheimer disease (2); Ataxia (2); autism spectrum disorder (2); cholangiocarcinoma (2); COVID-19 (2); Huntington disease (2); Macrocephaly (2); Parkinson disease (2); stomach cancer (2); AIDS (1); amyotrophic lateral sclerosis (1); attention deficit-hyperactivity disorder (1); autosomal dominant polycystic kidney disease (1); B-cell lymphoma (1); behavioral disorders (1); bladder cancer (1); cervical tumour (1); chronic lymphocytic leukemia (1); chronic myeloid leukaemia (1); Coma (1); cryptococcosis (1).
A further 36 diseases each share a sentence with CSNK2A1 in 1 paper.